ALB (albumin)
Diseases named in the same sentence as ALB in open-access papers (continued):
Sharing a sentence is not in itself a finding about the gene and the disease.
tumor (continued). "Collectively, the dual tumor-targeting feature of the Pt NPs, comprising both passive targeting via the EPR effect and active targeting via albumin/SPARC signaling, makes the Pt NP a promising candidate for NP-mediated drug delivery." (PMID 31992692, 2020). "All tested models included parameters for liver function (ie albumin, bilirubin, AST), most of them included tumour‐related parameters (ie AFP, tumour size, macrovascular invasion) and some included ‘other’ baseline parameters (age, HCC aetiology, ECOG PS)." (PMID 31579990, 2020). "Using MRI enhanced with an intravascular contrast agent, albumin-Gd-DTPA, they measured significant decreases in contrast enhancement 24 h after crolibulin treatment in both tumor models." (PMID 32879326, 2020). "There were significant differences between the intervention and control groups in present illness (tumour), CRP, albumin, dressing films, level of nurse experience, number of catheterizations catheterization times”, and hyperosmotic solutions." (PMID 32005839, 2020). "In tumor T4, the uptake of the albumin-bound [68Ga]ABY-028 was, similar to the [18F]FDG profile, much more heterogeneous than in tumor T1." (PMID 32960353, 2020). "In this work, we report an optimized phototheranostic nanocomplex (NC) that is rationally assembled from bovine serum albumin (BSA) and ICG for enhanced NIR fluorescence imaging guided PTT on tumor." (PMID 32183838, 2020). "Changes in tumor marker (alpha-fetoprotein (AFP)/des-gamma-carboxy prothrombin (DCP)) levels and albumin–bilirubin (ALBI) score between the baseline value and that estimated one month after treatment were evaluated." (PMID 32218295, 2020). "The main points of this paper are that the up-to-seven criteria (the combination of tumor size and number), AFP level as malignant potential, and albumin level as liver function can be used to select patients with intermediate HCC for HR." (PMID 33112547, 2020). "An exploratory univariable analysis showed that albumin, Ln(bilirubin), ECOG PS, macrovascular invasion, extrahepatic spread, largest tumour size, number of liver lesions, Ln(AFP) and receiving prior HCC treatments were associated with OS." (PMID 31579990, 2020). "The univariate analysis revealed that the performance status, tumor location, curative surgery, hemoglobin, TLC, albumin level, BMI, PNI, NRI, NLR, PLR, LMR, and LBMI were significantly associated with the one year mortality rate of LAHNC patients." (PMID 32245095, 2020). "Proceeding to conversion surgery, albumin level, log10 (CA19‐9), log10 (tumor size), CA19‐9‐lowering rate, and tumor size‐lowering rate were predictive factors for OS." (PMID 32021953, 2020). "Cox regression analyses revealed that a tumour number equal to or greater than two (HR 1.54), AFP > 400 μg/l (HR 1.14), serum albumin < 3.6 g/dl (HR 1.63) and total bilirubin > 0.9 mg/dl (HR 1.58) were independent risk factors in our population." (PMID 32125515, 2020). "In accordance with the HAP score, it contained the parameters albumin (< 36 g/dl) and bilirubin (> 17 μmol/l) for liver function, AFP (> 400 ng/dl) and tumour size (> 7 cm) for tumour burden and additionally rated the lesion number (≥ two)." (PMID 32125515, 2020). "Therefore, albumin levels could be used to reflect tumor prognosis." (PMID 33014783, 2020). "The optimal cutoff values determined by the ROC curve analysis were 5.0 cm for tumor size, 2.05 for NLR, 177.6 for PLR, 0.815 for S/L ratio, 12.5 g/dL for hemoglobin, and 3.9 g/dL for albumin for the RFS." (PMID 30718566, 2019). "As the primary goal of the conjugation to albumin consists of preserving the inhibitory compound in the circulation to maintain a sustained PACE4 inhibition in vivo, the pharmacokinetic and tumor-targeting properties of prodrug 2 were examined." (PMID 30765725, 2019).
tumor (continued). "Before matching, there were significant differences in aspects of BMI, preoperative HGB, preoperative albumin, ASA, comorbidity, tumor location, differentiation (P < 0.05) between the open group and laparoscopic group." (PMID 31521147, 2019). "They show that age, ECOG, aetiology, tumour size, extra-hepatic spread, vascular invasion, log(bilirubin), log(AST), log(AFP), albumin and INR were statistically significant prognostic factors." (PMID 31182766, 2019). "In univariate analyse, Age, TNM stage, tumor stage, node stage, distant metastases, LDH, GGT, TBA, ALP, ALB, ApoB, Fbg were related to OS." (PMID 30909980, 2019). "In this study, we first analyzed the correlations of GAR and clinicopathologic characteristics and we found that GAR was closely correlated with tumor location, tumor size, vascular invasion, obstructive jaundice, biliary drainage, ALP, ALT, AST, GGT, and ALB." (PMID 30632317, 2019). "Univariate analysis showed albumin, bilirubin, GGT, ALT, prothrombin time, AFP, tumor size of the largest nodule, and combined treatment to be statistically significant factors affecting survival." (PMID 31777583, 2019). "The initial model (Model 1) included six variables of gender, age, albumin, bilirubin, GGT, tumor size of the largest nodule." (PMID 31777583, 2019). "According to univariate analyses of baseline variables, the ECOG score, the tumour size, the number of HCC nodules, PVTT, EHS, ascites, the AFP level, the albumin level, the total bilirubin level and the AST level were significantly associated with OS." (PMID 31815114, 2019). "PAI using ICG has been proven to provide early detection of neoangiogenesis in growing neoplasia such as a Lewis lung carcinoma mouse model, based on EPR effect exerted by ICG-albumin macromolecules within the tumor environment." (PMID 31182936, 2019). "Our prediction model includes the variables of albumin, bilirubin, GGT and tumor size treated as continuous variables." (PMID 31777583, 2019). "FA-modified albumin nanoparticles were a good carrier for delivering SRF, which was relatively enriched in tumor tissue and can improve the therapeutic effect and reduce the side effects of the drug." (PMID 30744448, 2019). "To confirm the antibacterial activity of the examined GO-nanocomposites, we examined their interactions with bovine serum albumin (BSA) and circulating tumor DNA (ctDNA) by steady-state fluorescence spectroscopy." (PMID 35518070, 2019). "In the univariate analysis of OS and DFS, the significant prognostic parameters are tumor size, TNM stage, treatment exposure, serum AFP level, serum CRP level, serum albumin level, albumin / CRP ratio, and platelet / CRP ratio." (PMID 31164099, 2019). "To determine the effects of tumor cells themselves on edema, we first established TEER as a surrogate for BBB leakiness by demonstrating that passage of albumin strongly correlated with decreased TEER (R = -0.69, P = 0.0045)." (PMID 31362777, 2019). "In order to confirm the antibacterial activity of the fabricated nanocomposites, the fluorescence quenching of bovine serum albumin (BSA) and circulating tumor DNA (ctDNA) were examined using the steady-state fluorescence technique." (PMID 35518070, 2019). "In this regard, Gd3+ ions chelated diethylenetriaminepentaacetic acid (DTPA-Gd3+) have been conjugated with bovine serum albumin (BSA) and CuSNPs, to act as the contrast agent for tumor detection by PAI and MRI." (PMID 31182936, 2019). "Immunofluorescence micrograph demonstrated that the FITC-labeled nanoparticles colocalized with SPARC in tumor (lower row), supporting the tumor targeting effect of BPBBT NPs through the albumin-SPARC binding." (PMID 31101816, 2019). "In our previous study, CYC loaded bovine serum albumin (BSA) nanoparticles showed effective and enduring tumor tissue accumulation and extracellular retention which increase binding of CYC and SMO membrane receptors." (PMID 31867309, 2019).
tumor (continued). "The optimal cutoff values determined by the ROC curve analysis were 3.7 cm for tumor size, 2.17 for NLR, 145.4 for PLR, 0.731 for S/L ratio, 11.5 g/dL for hemoglobin, and 3.8 g/dL for albumin for the OS." (PMID 30718566, 2019). "In the multivariate analysis, the results indicated that tumor size, TNM stage, treatment exposure, serum AFP level, and albumin / CRP ratio were independent factors for HCC prognosis." (PMID 31164099, 2019). "Our previous study using CORM2 and polymer conjugated hemin (PEG-hemin) showed the increased tumor delivery of macromolecules (Evans blue bound albumin) by these CO generators, by virtue of the improved EPR effect and the restoration of the tumor blood flow." (PMID 31315251, 2019). "The bovine serum albumin (BSA) conjugated S0456, BSA-S0456 control showed poor specificity to tumor and majority of the dye is accumulated in the liver as compared to the tumor." (PMID 30781490, 2019). "In the present study, we assessed the perioperative and prognostic importance of indocyanine green (ICG) testing, tumor‐node‐metastasis (TNM) stage, albumin‐bilirubin (ALBI) grade, and ALBI‐TNM (ALBI‐T) score using consecutive resected HCC cases." (PMID 30697612, 2019). "It is generally recognized that several factors, such as tumor length, vessel invasion, CRP, ALB, PALB, CAR, CPR, and TNM stage, were significantly associated with CSS in univariate analyses." (PMID 31379941, 2019). "Studies showed that Serum Albumin (ALBU) and Apolipoprotein A-I (APOA1) proteins were up-regulated in grade III astrocytomas, facilitating tumor proliferation through an increase in neovascularization and migration of tumor cells." (PMID 31357616, 2019). "Significant differences were observed in the BMI, AST, ALB, TBIL, PT, APTT, and AFP levels, the antiviral therapy, tumor size, vascular invasion, metastasis, and BCLC Stages between the short‐ and long‐term survival groups." (PMID 31313476, 2019). "Therefore, taking this into consideration, it is possible that albumin bound lignans may accumulate in the tumor environment independently and/or released upon albumin catabolism, e.g., similar to albumin conjugated drugs used for increasing intratumoral accumulation of drugs for antitumor effects." (PMID 31060335, 2019). "A different approach using human serum albumin (HSA) nanoparticles stabilized with intramolecular disulfide bonds and modified by substance P (SP) tumor-targeting peptide to deliver paclitaxel (PTX) to U87 orthotopic xenografts." (PMID 30619758, 2018). "We used multivariate analysis to further analyze the factors that are significant in univariate analysis, including the primary site of the tumor, the degree of differentiation, the levels of SLA, LDH, ALB, and CA199." (PMID 30627541, 2018). "At the pre-operative stage, SSI was associated with DM, pre-operative radiotherapy, tumor location, tumor stage, WBC, neutrophil percentage, Cr, heart disease, primary tumor, albumin, CVA, and recurrent tumor." (PMID 29568393, 2018). "Albumin values were lower in the patients with PVT, but significant only for the small tumor groups." (PMID 30009156, 2018). "Multivariate Cox's regression analyses revealed that the total bilirubin level, serum albumin level, HBV-DNA, and tumor number served as statistically significant predictors of OS." (PMID 29765560, 2018). "Under inflammatory conditions, immune cells and tumor cells release various inflammatory mediators, including interleukin-1β, interleukin-6, and tumor necrosis factor (TNF), which can suppress albumin synthesis in liver cells." (PMID 29685957, 2018). "Variables with P<0.20 in the univariate analysis (total bilirubin level, serum albumin level, AST level, HBV-DNA, HCV-RNA, Child-Pugh grade, tumor number, and BCLC stage) were subjected to the multivariate analysis." (PMID 29765560, 2018).
tumor (continued). "A logistic regression model of PVT showed significance for several single parameters as continuous variables, but when all parameters were considered together, there was significance in the final model for tumor multifocality, MTD, AFP, ALKP, and albumin." (PMID 30009156, 2018). "Cox’s regression analysis was performed on several variables, including age, sex, BMI, alcohol consumption, smoking status, tumor location, tumor size, CA19.9, chemotherapy, albumin, hemoglobin, WBC, platelet count, MPV, and PDW." (PMID 29662100, 2018). "The primary tumor occurred in colon (P = 0.002), LDH≥225U/L (P = 0.011), ALB<40g/L (P = 0.003), and low degree of pathological differentiation (P = 0.028) were poor prognostic factors for OS of patients with mCRC." (PMID 30627541, 2018). "Multivariate analyses followed by univariate analyses revealed that serum bilirubin level (P=0.032), serum albumin level (P=0.008), HBV-DNA (P=0.013), and tumor number (P=0.021) were independent predictors of OS." (PMID 29765560, 2018). "Univariate analysis showed that AST levels, albumin levels, PT, AFP levels, tumor size, and treatment methods significantly affected the OS of patients." (PMID 30095644, 2018). "And the Kaplan-Meier statistical analysis was used to analyze the survival curves of patients with different LDH, ALB, SLA, CA199, and primary tumor sites." (PMID 30627541, 2018). "Univariate analysis showed that SML; serum level of total bilirubin ≥1.5 mg/dL, albumin < 3.5 g/dL, and AFP ≥ 20 ng/mL; maximum tumor diameter ≥ 30 mm; and progressive disease in response to treatment were significantly associated with poor OS." (PMID 30041616, 2018). "The molecule is also able to bind human serum albumin (HSA), conferring it with an increased serum half-life and potentially enhanced tumor penetration." (PMID 28271446, 2018). "Unlike TNM staging, which depends purely on anatomic extent of the tumor, the ALBI grade belongs on the other end of the spectrum and uses only albumin and bilirubin as a measure of hepatic function." (PMID 29766659, 2018). "The baseline patients’ demographics before PSM showed significant differences in terms of ALB (median, 42.3 vs. 40.6 g/L, p = 0.027), PLT (median, 127.0 vs. 99.0 109/L, p = 0.013), and tumor size (median, 4.3 vs. 6.0 cm, p = 0.036), respectively." (PMID 28726140, 2018). "Tumor location, TNM classification, the level of baseline total bilirubin (TBIT), direct bilirubin (DBIT), albumin (ALB), globulin (GLOB), total protein (TP), ALB to GLOB ratio (AGR), CA19‐9, CA242, and CA50 were collected." (PMID 30474926, 2018). "Other significant prognostic parameters included the CRP, AST, ALB, ALP, GGT, and AFP levels, the tumor diameter and vascular invasion." (PMID 28355305, 2017). "In univariate analysis, levels of AST, ALB, ALP, CRP, AFP, and NLR, tumor size, tumor number, metastasis, vascular invasion, antiviral therapy, and TACE with H101 were significantly associated with OS." (PMID 28728568, 2017). "Trafficking of 111Indium-labeled CART72 cells was compared to tumor uptake of infused technetium albumin aggregated particles (99mTc-MAA), which visualize vascularized tumor tissue." (PMID 28344808, 2017). "The nomogram illustrated tumor size as sharing the largest contribution to prognosis, followed by tumor stage, HBV infection status, ALB, CA 19-9, ALT, and age." (PMID 28912447, 2017). "Paclitaxel (PTX), especially albumin-bound PTX in clinical, has displayed significant inhibition of tumor growth in patients." (PMID 28428562, 2017). "In order to understand the molecular mechanism of SMAD7 as a tumor suppressor in the development of HCC, Tamoxifen-inducible hepatocyte-specific SMAD7 expression was induced or blunted using albumin promoter-driven constructs in SMAD7 Tg and SMAD7 KO mice." (PMID 28134936, 2017).
tumor (continued). "Our multivariable analysis showed that the key variables influencing survival were related to tumour characteristics (tumour size, tumour number, AFP and VI), liver function (albumin and bilirubin) and aetiology." (PMID 28125820, 2017). "As results, seven independent prognostic factors were identified: age, tumor stage, tumor size, ALT (alanine aminotransferase), ALB (albumin), CA 19-9, HBV infection status, and these factors were entered into the nomogram." (PMID 28912447, 2017). "A univariate Cox regression analysis showed that preoperative albumin (ALB), American Society of Anesthesiologists (ASA) score, CCI, tumor size, mitotic rates, tumor resection methods, and IM treatment were pretty related to the 5-year OS." (PMID 28383420, 2017). "Older age (≥60 vs. <60, P < 0.001), stage IV (vs. III, P < 0.001), larger tumor size (P < 0.001), elevated ALT (vs. normal, P < 0.001), low ALB (vs. normal, P < 0.001), and elevated CA 19-9 (vs. normal, P < 0.001) were associated with poor prognosis." (PMID 28912447, 2017). "After treating the continuous variables, including levels of AFP, ALB, and ALP, and tumor size, as dichotomous variables, significant independent risk factors were integrated to develop the nomogram for predicting the OS of the study cohort." (PMID 28728568, 2017). "In this study, we identified seven independent prognostic factors for advanced PDAC, namely, age, tumor stage, tumor size, ALT, ALB, CA 19-9, and HBV infection status." (PMID 28912447, 2017). "In contrast, B-22956/1 (86kDa), another contrast agent that binds reversibly to albumin, was enhanced 10 fold in the tumor rim after anti-angiogenesis therapy when compared to Gd-DTPA-albumin, and was also detected in the tumor core." (PMID 28415647, 2017). "Accordingly, the enhanced tumor accumulation of CNCs mainly resulted from the prolonged circulation time, EPR effect and specific binding of albumin with cancer cells." (PMID 28383524, 2017). "A protein secreted by the tumor, secreted protein acidic and rich in cysteine (SPARC) is postulated to bind and entrap the albumin, allowing release of the hydrophobic drug to the tumor cell membrane." (PMID 28881739, 2017). "Tumor grade, T, N, and M stage, treatment approach, and TBIL, IBIL, and albumin level were included in the nomogram for both the training and validation cohorts." (PMID 28476041, 2017). "Increasing evidence of the prognostic value of preoperative CRP, albumin, and GPS support their utility for clinical decision-making in evaluation of postoperative survival, possibly combined with tumour markers." (PMID 27632196, 2016). "The HAP score consists of two measures of tumor burden (AFP and size of largest tumor) and two measures of liver function (albumin and bilirubin)." (PMID 27601241, 2016). "In this study, the value of the serum tumor markers CA19.9, CEA, CRP, albumin, IGF-1 and IGFBP3 alone or in combination, in the differential diagnosis of PDAC and CP was assessed." (PMID 26808421, 2016). "In conclusion, although the mechanisms by which SPARC regulates tumor growth are complex, we show the importance of the biological role of SPARC as a chaperone for serum albumin." (PMID 27776337, 2016). "Univariate analysis revealed that AEG patients with hemoglobin ≥120 g/L, albumin ≥40 g/L, pre-albumin ≥200 g/L, PNI ≥51, and tumor size <5 cm had longer OS (P < 0.05)." (PMID 27809860, 2016). "Japanese retrospective study has also revealed that seven factors (distant metastases, portal invasion, intrahepatic tumor burden, serum AFP, DCP, albumin and total bilirubin) were independently related to a worse survival." (PMID 26931117, 2016). "By enhancing the transport of albumin from the vascular space to tumors, SPARC mediates lipid deposition in tumor tissue, leading to lipotoxicity." (PMID 27776337, 2016).